HPSE (heparanase)
Diseases named in the same sentence as HPSE in open-access papers (continued):
Sharing a sentence is not in itself a finding about the gene and the disease.
tumor (continued). "Together, these findings indicate that nuclear heparanase plays an important role in tumorigenesis by promoting chromatin remodeling that opens its conformation, allowing access to promotors of genes that drive tumor progression." (PMID 36980232, 2023). "The actions of ECM-modulating enzymes such as HPSE may have a profound impact especially in the early stages of tumour development, translating to clinically obvious effects in advanced stages of cancer." (PMID 37297024, 2023). "The combined involvement of heparanase in epigenetic gene regulation and tumor progression has been further elucidated in studies demonstrating that chemotherapy, in addition to its cytotoxic effects on tumor cells, can support tumor re-growth and spread." (PMID 36980232, 2023). "However, heparanase-2 inhibits heparanase enzymatic activity and appears to function as a tumor suppressor." (PMID 36980254, 2023). "In the tumor microenvironment, the expression levels of various enzymes such as metalloproteinase, heparanase, and proteases, can undergo changes that can be utilized for achieving targeted drug accumulation at tumor sites through enzyme-responsive drug release." (PMID 37483271, 2023). "Indeed, overexpression of heparanase in mice promotes tumor initiation and growth and stimulates inflammatory responses." (PMID 36980232, 2023). "Likewise, increased Heparanase concentrations have been shown to promote tumor growth for glioma, mesothelioma and gastric carcinoma cells." (PMID 36986571, 2023). "Heparanase is one of the main regulators of aggressive tumor behavior." (PMID 36980254, 2023). "Moreover, in these tumor types, inhibitors of heparanase have exerted anti-cancer effects in preclinical models and are currently being tested clinically." (PMID 36979689, 2023). "Indeed, early on, heparanase activity was found to correlate with the metastatic potential of tumor cells, a correlation that still directs and guides heparanase research." (PMID 37547889, 2023). "Notably, tumor xenografts produced by C‐domain‐transfected glioma cells appeared comparable to those produced by cells transfected with the full‐length heparanase." (PMID 37547889, 2023). "Some other experimental studies have even tried to benefit from the ECM degradation capacity of heparanase-1 by engineering tumor-specific CAR (chimeric antigen receptor) expressing heparanase-1, which are capable of infiltrating stroma-rich solid tumors and of specifically killing cancer cells." (PMID 36680276, 2023). "HPSE, which traditionally functions extracellularly by cleavage of heparan sulfate and promoting the remodeling of the extracellular matrix (ECM), has long been associated with an increase in tumor metastasis and angiogenesis." (PMID 37508554, 2023). "Indeed, a study on cell invasion into a three-dimensional matrix showed that clones with heterozygous deletions in HPSE and reduced HPSE expression exhibit a marked decrease in tumor cell invasion and cell adhesion to laminins." (PMID 36980765, 2023). "To date, heparanase, an endoglycosidase able to cleave heparan sulfate from HSPGs, is one of the most investigated proteases involved in cancer, correlating with tumor angiogenesis, metastasis, and reduced survival across numerous cancers in various organ systems." (PMID 37688612, 2023). "The mechanism of action of these HS-mimetics is primarily mediated via inhibition of heparanase-mediated angiogenesis and metastasis, competitive binding with growth factors, and/or activation of tumor-suppressing immune cells (e.g., natural killer and dendritic cells)." (PMID 36980680, 2023). "Indeed, recent studies reported the correlation of heparanase expression levels with a higher degree of the tumor, late stage, advanced tumor angiogenesis, and low patient survival." (PMID 36340029, 2022). "Furthermore, our results show that heparanase can be found elevated in non-tumor adjacent tissue in a stage-dependent manner." (PMID 36139645, 2022).
tumor (continued). "HPSE-2 appears not only to be able to inhibit HPSE activity but also regulate a multitude of signaling pathways that mediate cell differentiation, apoptosis and tumor vascularity, leading to tumor suppression." (PMID 36157032, 2022). "While HPSE is only expressed at low levels under physiologic conditions, it is overexpressed in pathologic conditions such as inflammation, injury, fibrosis, and tumor progression." (PMID 35073921, 2022). "Moreover, heparanase enhances autophagy, and this process favours tumour growth and chemoresistance." (PMID 34982945, 2022). "Heparanase plays important roles in tumor growth, correlates with the metastatic potential of cancer cells and, as such, has generated interest as a potential target against tumor development." (PMID 36428962, 2022). "Furthermore, tumor tissue stage II heparanase levels were higher than tumor tissue stages I, III, and IV." (PMID 36139645, 2022). "HPSE protein is a multifunctional cancer-promoting molecule and through its enzymatic activity, it hydrolyzes heparan sulfate to trigger remodeling the extracellular matrix, promote invasion and metastasis, and induce changes in the tumor microenvironment." (PMID 36130926, 2022). "Therefore, downregulation of both uPA and heparanase by isatin derivatives (3a, 4b, and 4c) highlights their promising anticancer activities via targeting tumor invasion and metastasis." (PMID 35327524, 2022). "That scenario explains the relevant role of heparanase because once released, tumor-derived exosomes can travel through the body and impact resident cells at locations distal to the tumor, thereby aiding in the preparation of the pre-metastatic niche and influencing metastatic organotropism." (PMID 36340029, 2022). "Heparanase (HPSE) is a potent enzyme that fosters tumor growth, angiogenesis, and metastasis." (PMID 36249037, 2022). "Reduction in heparanase expression as well as prevention of HSPG expression on tumor cells has been shown to reduce tumorgenicity in vivo, highlighting their importance in retaining a malignant phenotype as well as making them attractive targets for therapeutics." (PMID 36016277, 2022). "Xenograft models further confirmed the role of HPSE in tumor growth." (PMID 36130926, 2022). "There is an opinion that the beneficial effect of heparin on tumor patients is multifactorial and may involve mechanisms other than those mediated by growth factors and their receptors, heparanase, and selectins." (PMID 36297616, 2022). "This gene encodes HPSE protein which performs multiple functions independent of its enzymatic activity in tumor cells and the tumor microenvironment." (PMID 36130926, 2022). "HPSE knockdown impeded tumor proliferation of BRAF V600E-mutant CRC cells in vitro and in vivo." (PMID 36130926, 2022). "Thus, overexpression of HPSE in cancers promotes tumor growth and metastasis, leading to poor clinical prognosis." (PMID 36340029, 2022). "Moreover, heparanase levels also increased in stage II in tumor tissue contributing to the perpetuation of the inflammatory status besides its role in metastasis." (PMID 36139645, 2022). "Heparanase is known to play a decisive role in tumor metastasis and angiogenesis." (PMID 34685503, 2021). "Besides MMPs, heparanase, another enzyme responsible for ECM degradation and remodeling, and found to be upregulated in several tumor types in association with the presence of metastases, was considered as an interesting target." (PMID 34298680, 2021). "Importantly, as both SDC-1 and heparanase participate in exosome generation, heparanase inhibition reduces tumor growth as well as exosome-derived tumor recurrence." (PMID 35118073, 2021). "Indeed, later studies found that targeting heparanase can re-sensitize resistant tumor cells to chemotherapy and inhibit tumor cell growth in vitro and in vivo, presenting a promising approach to enhance chemotherapy response." (PMID 34681753, 2021).
tumor (continued). "In a tumor setting, heparanase enhances the phosphorylation of STAT3 and STAT5b." (PMID 34681753, 2021). "Heparanase is an endoglycosidase that plays a critical role in tumor progression and metastasis." (PMID 34199150, 2021). "Tumor-associated macrophages (TAMs) and CC-chemokine receptor 1 (CCR1)+ immature myeloid cells are responsible for the tumor invasion through IL-4-dependent secretion of matrix-degrading enzymes such as MMPs, cathepsins, and heparanase." (PMID 34220337, 2021). "Efficient heparanase activity depends on the microenvironment pH, since a pH of approximately 7 leads to inactivation of heparanase, but an acidic pH of between 5 and 6 provides its optimal activity during tumour growth and in pro-inflammatory conditions." (PMID 34070058, 2021). "Interestingly, both heparanase activities are equally involved in cancer invasion and dissemination, allowing neoplastic cells to invade the tumour site locally and spread to distant sites." (PMID 34070058, 2021). "Thus, overexpression of heparanase correlates positively with the invasion and spread of cancer cells as well as inflammation, procoagulant state and neovessel formation within the tumour." (PMID 34070058, 2021). "The reduced tumor growth and metastasis in mice were observed in heparanase knockdown mice." (PMID 34220326, 2021). "Examples include chemically modified N-desulfated, N-acetylated and glycol-split heparin derivatives and a heparanase inhibitor, that alone or together with lapatinib, resulted in inhibition of the tumor growth in patients with myeloma or in brain metastatic breast cancer, respectively." (PMID 33430152, 2021). "The expression of heparanase in Salmonella-treated tumor cells was found to be decreased." (PMID 34220326, 2021). "HPSE has been shown to be an important player in tumor progression and metastasis." (PMID 34578329, 2021). "There were 641 ER+ tumor TMAs available for evaluation of heparanase by IHC." (PMID 34050190, 2021). "Finally, NF-κB, a potent transcription factor downstream of many signaling pathways, can also increase heparanase expression in tumor cells." (PMID 34681753, 2021). "When heparanase is downregulated, it can inhibit tumor metastasis." (PMID 33917849, 2021). "Moreover, heparanase enzyme secreted from the tumor cells degrades endogenous heparin, potentially contributing to the hypercoagulability in patients with cancer." (PMID 33490732, 2021). "Heparanase demonstrates strong implications for tumour aggressiveness and dissemination." (PMID 34070058, 2021). "Given the pro-angiogenic properties of macrophages, their elimination from the tumor mass may add another explanation for the observed impaired angiogenesis in heparanase-KO mice or following pixatimod (PG545) treatment." (PMID 35069219, 2021). "Heparanase expression is elevated in several types of tumors and this high expression pattern is mostly related to aggressive type of disease, poor prognosis, as well as increased tumor metastasis." (PMID 33917849, 2021). "Therefore, heparanase is a viable target for tumor therapy and anti-heparanase is a promising anticancer agent." (PMID 34220326, 2021). "Interestingly, the use of heparanase inhibitors showed to block tumor progression by reducing exosome uptake by receptor cells." (PMID 33430152, 2021). "Heparanase is a multifunctional protein that influenced metastasis and tumor growth." (PMID 34220326, 2021). "It seems that LMWHs can affect circulating tumor cells and the tumor micro-environment (TME) through various mechanisms including the effects of heparan sulfate proteoglycans/heparanase on metastasis formation, angiogenesis/tumor vasculature, and immune-suppressive/therapy-resistant TME." (PMID 34207591, 2021). "This supports a role for heparanase in driving tumour progression." (PMID 33922532, 2021). "Furthermore, HPSE mediates the establishment of a vascular network that promotes primary tumor growth and metastatic cells invasion." (PMID 34578329, 2021).
tumor (continued). "Also, in combination with dexamethasone it was able to inhibit myeloma tumor growth in vivo through dual targeting of the tumor and its microenvironment via the heparanase/syndecan-1 axis." (PMID 31963505, 2020). "Therefore, it is vital that the precise role of HPSE in a given tumour setting is elucidated, with its pro and anti-tumour roles thoroughly addressed prior to the use of HPSE inhibitors." (PMID 33256730, 2020). "Heparanase expression is often induced in carcinomas and is associated with increased tumor metastasis and bad prognosis, but the effect of heparanase on AJ has not been reported yet." (PMID 32038981, 2020). "Heparanase-neutralizing antibodies have been suggested for the treatment of diffuse non-Hodgkin’s B-cell and follicular lymphomas through the inhibition of cell invasion and tumor metastasis processes." (PMID 32471161, 2020). "In addition, heparanase promotes tumor vascularization (blood and lymph vessels) that mobilize disseminating cells to distant organs." (PMID 32038981, 2020). "Furthermore, cathepsin L was co-expressed with heparanase-1 and transformed inactive heparanase-1 form into active heparanase-1, triggering extracellular matrix remodeling, which contributes to enhanced tumor-host interaction of the tumor." (PMID 33053017, 2020). "A study involving human and mouse NK cells demonstrated that HPSE expression was significantly upregulated upon NK cell activation and that mice lacking NK cell-specific HPSE expression exhibited impaired invasion and tumour surveillance." (PMID 33256730, 2020). "Furthermore, heparanase neutralizing monoclonal antibodies attenuate myeloma and lymphoma tumor growth and dissemination." (PMID 32916872, 2020). "It was also shown that its tumor suppressor action occurs by downregulation of heparanase (HPSE), a mammalian endoglycosidase with tumorigenic, angiogenic and pro-metastatic activity that is highly expressed in cancer cells with high propensity to colonize the brain." (PMID 32731349, 2020). "In addition, HS mimetics as well as antibodies, and other modulators have been developed to target heparanase and sulfatases involved in the regulation of HSPGs in tumor microenvironment." (PMID 32916872, 2020). "This pivotal study has shed light on a previously unknown role of HPSE in regulating NK cell-mediated tumour immunosurveillance." (PMID 33256730, 2020). "Hpa2 thus competes with heparanase and has been shown to act as a tumor suppressor." (PMID 32937952, 2020). "This is mainly due to the degradation of endogenous heparin by tumor-secreted heparanase." (PMID 32121387, 2020). "The heparanase is involved in the hinokitiol-mediated tumor inhibition." (PMID 32132875, 2020). "Additionally, by diminishing the phosphatase activity of PTEN, thereby blocking its function as a tumor suppressor, heparanase ensures further activity of biological pathways that enhance tumor growth, progression and resistance to therapy." (PMID 32899927, 2020). "Additionally, heparanase is involved in tumor angiogenesis, invasion and metastasis, and a number of studies suggest that heparanase is a viable target for cancer therapy." (PMID 32538273, 2020). "HPSE also bypasses the tumour-suppressive roles of several genes, such as PTEN, STAT3 and TGF-β." (PMID 33256730, 2020). "However, recent discoveries which demonstrated that heparanase can also regulate vital anti-tumour mechanisms have cast doubt on this approach." (PMID 33256730, 2020). "Preclinical studies have shown a significant reduction in tumor volume compared to that of plain nanoparticles, suggesting that heparanase aptamer may be a promising target for TNBC drug delivery." (PMID 32521684, 2020). "Therefore, in a rather interesting twist, the intracellular activity of HPSE is suggested to mediate tumour cell survival through promoting autophagy, a mechanism designed to maintain cellular homeostasis." (PMID 33256730, 2020).
tumor (continued). "In addition, heparanase enhances the formation of new blood and lymph vessels, thereby promoting the mobilization of disseminating tumor cells to distant organs." (PMID 32038981, 2020). "We transfected tumor cells with constitutively active Akt plasmid to increase Akt transcription and phosphorylation and then observe whether heparanase will upregulate because of high phospho-Akt expression levels." (PMID 32132875, 2020). "Furthermore, cathepsin L transforms inactive heparanase-1 form into active heparanase-1, both trigger extracellular matrix remodeling, which contributes to enhanced tumor-host interaction of the tumor." (PMID 33053017, 2020). "Furthermore, hinokitiol also downregulated the Akt phosphorylation and heparanase expression of Akt-transfected tumor cells." (PMID 32132875, 2020). "A body of evidence indicates that the altered expression or activity of heparanase determines a profound impact on tumor behavior; indeed, heparin analogs able to inhibit heparanase have been developed to primarily target cancer and some proved very active and have been tested in clinical trials." (PMID 31963505, 2020). "HPSE is a potent regulator of tumour inflammation, especially mediating TAM activity." (PMID 33256730, 2020). "In addition, as its genetic knockdown in experimental disease models significantly curtails tumor progression, it can be concluded that heparanase is a valid cancer drug target." (PMID 31850210, 2019). "The link between heparanase and PDAC progression is well-established and the underlying molecular/cellular mechanisms include increased invasiveness and creation of tumor-promoting inflammatory environment." (PMID 31921662, 2019). "However, targeting heparanase via a vaccine approach will rely on tumors maintaining heparanase expression to allow T cell recognition of heparanase-positive tumor cells." (PMID 31110966, 2019). "The heparan sulfate-activated lymphocytes overexpressed HPSE, and this might have increased cellular migration, which is highly relevant for tumor metastasis." (PMID 30922347, 2019). "Furthermore, it was demonstrated that the protein composition of exosomes was modified by an increase in heparanase in an aggressive type of tumor." (PMID 30922347, 2019). "Such proteins could affect ECM remodeling (e.g., heparanase), or be overexpressed on the tumor vasculature and/or tumor cells (e.g., EMMPRIN)." (PMID 31440262, 2019). "Heparanase can enhance the growth, metastasis, angiogenesis, and inflammation of tumor." (PMID 31438991, 2019). "Importantly, it has been demonstrated that in vivo the anti-heparanase drugs will act on heparanase secreted by both the tumor and the host, a fact that is often overlooked when assessing the in vivo data." (PMID 31850210, 2019). "Consistently, in vivo data showed that knockdown of HPSE suppressed tumor growth of CRC." (PMID 31001480, 2019). "Heparanase was shown to promote tumour cell proliferation, migration and evasion of apoptosis." (PMID 31044520, 2019). "Tumor growth and angiogenesis were further constrained when both mAbs were administered together implying that greater efficacy is achieved when two different epitopes on heparanase are targeted." (PMID 31850210, 2019). "On the contrary, heparanse-2 inhibits the activity of HPSE, thereby acting as a tumor suppressor." (PMID 31013618, 2019). "We will now discuss how heparanase may regulate leukocyte function in the context of tumor progression and its relevance in cancer therapy." (PMID 31110966, 2019). "The heparan sulfate secreted by activated lymphocytes and tumor cells, as well as heparan sulfate present in circulating exosomes, may promote the development of distantly located tumors by inducing heparanase expression." (PMID 30922347, 2019). "Heparanase present in the tumor microenvironment, either from malignant cells or activated T cells, was shown to promote viral “hand off” for the successful delivery of anti-tumor molecules to the tumor cells." (PMID 31110966, 2019).